IL6 (interleukin 6)
Diseases named in the same sentence as IL6 in open-access papers (continued):
Sharing a sentence is not in itself a finding about the gene and the disease.
ovarian carcinoma (continued). "The contribution of IL-6 to the neoplasia of ovarian cancer is mainly due to the potential overactivation of the Janus kinases and signal transducers and activators of transcription factor (JAK–STAT) signaling pathway." (PMID 34572929, 2021). "The databases were searched for the following keywords: ascites, ovarian cancer, cytokines, adipokines, adiponectin, interleukin 6 or IL-6, interleukin 8 or IL-8, MCP-1, TIMP-1, concentration, level." (PMID 34572929, 2021). "ADSC-produced IL-6 has been demonstrated to be responsible for increased autophagy and migratory capacity in ovarian cancer cells." (PMID 34440886, 2021). "IL-6 has been shown to activate the expression of stem cell markers and confers chemotherapy resistance and predict poor prognosis in ovarian cancer." (PMID 34588424, 2021). "Cancer-associated adipocytes, CAAs, exhibit an inflammatory phenotype, releasing cytokine/chemokine adipokines, i.e., leptin, adiponectin, interleukin-6 (IL-6), and IL-8 that contribute to ovarian cancer cell metastatic colonization." (PMID 34677277, 2021). "The interaction between IL-6 and sIL-6R has been shown to promote ovarian cancer progression through the ERK, a TK that triggers increased cell survival, migration and invasion." (PMID 34063231, 2021). "In this context, ASCs have been shown to enhance the migration of ovarian cancer cells through an IL-6-mediated pathway." (PMID 34912237, 2021). "It has been shown that IL-6 effectively induces the upregulation of B7-H4 on human macrophages in ovarian carcinoma." (PMID 33763491, 2021). "In fact, in patients with advanced ovarian cancer, we have demonstrated a correlation between high levels of IL-6 and the inability of lymphocytes to produce adequate level of IL-2 or express IL-2 receptor at physiological levels." (PMID 33550983, 2021). "TGF-β secretion can promote ovarian cancer metastasis, which stimulates CAFs to secrete cytokines and chemokines, including IL-6, CXCL10, and CCL5, that favor cancer cell metabolism and energy production." (PMID 34440886, 2021). "For IL-6 and IL-8, it can be confirmed that their concentrations in ascites in the course of ovarian cancer are higher than in blood plasma/serum." (PMID 34572929, 2021). "IL6 is known to promote cell growth, migration, neo-angiogenesis and chemotherapeutic resistance in ovarian cancer." (PMID 34238352, 2021). "Using a multiplex panel of 28 markers, the highest IL-6 concentration in blood serum was obtained in patients with advanced ovarian cancer, lower for patients with benign ovary conditions and the lowest for women with no such conditions." (PMID 34572929, 2021). "In a longitudinal study of ovarian cancer patients from whom tumor tissue was collected before and after chemotherapy, levels of IL-6 were elevated in αSMA+ stromal cells following platinum treatment." (PMID 34201616, 2021). "Notably, among the different tumors, ovarian cancer has the highest incidence of tumor-associated thrombocytosis and the strongest experimental and clinical evidence on the role of inflammation (particularly IL-6) in the development of this paraneoplastic condition." (PMID 33550983, 2021). "Siltuximab, the monoclonal antibody with a high binding affinity for IL-6, showed therapeutic activity in patients with platinum-resistant ovarian cancer in Phase II clinical trial." (PMID 34912809, 2021). "In the present study, we also demonstrated a statistically significant correlation between CA125 and IL-6 in ovarian cancer patients." (PMID 34573967, 2021). "Ovarian carcinoma cells also secrete pro-inflammatory mediators such as interleukin-6 (IL-6) which in turn promote tumor proliferation, invasion, and chemoresistance." (PMID 34078919, 2021). "We found a prevalence of M1 polarized macrophage with a M1/M2 ratio of 3.1, which was parallel with our previous findings in advanced ovarian cancer patients, associated with high circulating levels of CRP, IL-6, and ferritin, as well as lymphopenia." (PMID 33550983, 2021).
ovarian carcinoma (continued). "Norepinephrine can induce ovarian cancer cells to produce IL-6 and IL-8 through effects on the Src protein and FosB protein, respectively, and thus promote angiogenesis in ovarian cancer." (PMID 34307378, 2021). "IL-6 level in the control group was significantly lower than in patients with advanced ovarian cancer." (PMID 34572929, 2021). "Numerous studies of the concentration of IL-6 in the blood and ascites of patients with ovarian cancer confirm increased levels of this protein in neoplastic disease and the correlation of IL-6 secretion with the advanced stage of the disease." (PMID 34572929, 2021). "To this regard, we had demonstrated in patients with advanced ovarian cancer a positive correlation between high IL-6 levels and impaired nutritional status, as evidenced by low levels of leptin." (PMID 33550983, 2021). "Taken together, our study shows that M2 macrophages via IL-6 secretion, elevated PD-L1 and miR-21 expression which then promoted immune escape in ovarian cancer cells." (PMID 32927431, 2020). "Our results are consistent with the previously reported role of KLF-4 since we observed that DMU-214 increased KLF4 as well as IL6 transcripts level in SKOV-3 ovarian cancer cells." (PMID 32046103, 2020). "On the other hand, miR-21 containing EVs secreted by ovarian cancer cells are absorbed by M2 macrophage to further induce expression of IL-6 in a positive feedback loop." (PMID 32927431, 2020). "SNHG12 facilitated ovarian immune escape by promoting IL-6/miR-21 crosstalk between ovarian cancer cells and M2 macrophages." (PMID 32927431, 2020). "Jiang B reported that miR-217 inhibited tumor-induced M2 macrophage polarization by targeting IL-6 and regulating the JAK3/STAT3 signaling pathway, probably providing an underlying therapeutic target in the treatment of ovarian cancer." (PMID 33392180, 2020). "Increased serum levels of IL-6 have also been observed in patients with cancer, including breast, colorectal, stomach, and pancreatic cancers; malignant mesothelioma; and ovarian cancer." (PMID 33062717, 2020). "In the present study, the median IL-6 level was 24-fold higher in advanced ovarian cancer patients than those with normal ovaries." (PMID 32042020, 2020). "MSCs protect ovarian carcinoma cells from chemotherapy by secreting CCL5 and CCL2, which induce the release of IL-6 by ovarian carcinoma cells." (PMID 32630699, 2020). "NOD1 and NOD2 can induce an increase in IL-6 and NF-κB, which can enhance the metastasis and drug resistance of ovarian cancer." (PMID 32133297, 2020). "LPA regulates a variety of tumor-promoting factors and inflammatory factors in epithelial ovarian cancer, including IL-6, IL-8, VEGF, matrix metallopeptidases (MMPs), CXCL12, cytochrome c oxidase subunit 2 (COX2), uPA, cyclin D1, CXCL1." (PMID 32774171, 2020). "Ovarian cancer-derived TGF-β is involved in stimulating the production of various tumor-promoting factors including IL-6, CXCL12, and VEGF-A in the metastatic tumor microenvironment." (PMID 32546182, 2020). "The highest concentration of IL-6 was detected in the plasma of ovarian cancer patients, and it was significantly higher (p < 0.01) than in the control group." (PMID 33062717, 2020). "Recent data showed that autocrine production of the cytokine IL-6 confers cisplatin resistance in ovarian cancer cells." (PMID 31979221, 2020). "To investigate the effect of miR-21 containing EVs from ovarian cancer cells on IL-6 expression from M2 macrophages, we extracted and CFSE labeled EVs from SKOV3 and found that they are able to enter M2 macrophages." (PMID 32927431, 2020). "A high production of IL-6 by ovarian cancer cells contributes to tumor progression and correlates with a poor prognosis." (PMID 33266317, 2020). "Collectively, our data revealed that IL-6 secreted by M2 macrophages mediated PD-L1 and miR-21 expression in the ovarian cancer cell line SKOV3." (PMID 32927431, 2020).
ovarian carcinoma (continued). "IL-6 is a crucial cytokine in tumor progression and is demonstrated as a prognostic marker for monitoring ovarian cancer." (PMID 32190078, 2020). "Previous studies showed that high levels of IL-6 were found in the blood and ascitic fluid of ovarian cancer patients." (PMID 32927431, 2020). "Previously, our research team reported that adipose stem cells from visceral and subcutaneous fat facilitated the growth and migration of ovarian cancer cells via IL-6/JAK2/STAT3 pathway." (PMID 32121099, 2020). "Engagement of IL-6 in ovarian carcinoma cells phosphorylates PYK2, resulting in chemoresistance to carboplatin and taxanes." (PMID 32630699, 2020). "The IL-6 level remained at a highly detectable rate in all patients with advanced ovarian cancer, while the level was undetectable in 23.8% of patients with normal ovaries in the training phase." (PMID 32042020, 2020). "Autocrine IL-6 or IL-8 secretion by ovarian cancer cells induces resistance to paclitaxel and cisplatin, due to decreased proteolytic caspase 3 activation, increased Bcl-2 expression, and MAPK and PI3K/Akt pathway activation." (PMID 32499779, 2020). "Through peritoneal lavage component analyses of ovarian cancer, IL6 acted as an independent prognostic factor and correlated with the worst ovarian cancer prognoses." (PMID 33381581, 2020). "IL-6 was also described as a marker for platinum resistance in 32 EOC patients, and elevated levels of IL-6 in the serum and ascites of ovarian cancer patients at the time of diagnosis correlated with a poor initial response to chemotherapy and poor prognosis." (PMID 31979221, 2020). "Noteworthy, the level of IL-6 produced by mesothelial cells has been shown to be even 600-folds higher compared to ovarian cancer cells." (PMID 33062717, 2020). "The IL-6 -174 G/C SNP has been reported in many malignancies, including adenocarcinoma, lung, colorectal, gastric and ovarian cancers." (PMID 31991775, 2020). "In advanced epithelial ovarian cancer, high concentrations of IL-6, IL-10, growth-related oncogene-alpha, and vascular epithelial growth factor (VEGF) were associated with cell proliferation of human ovarian cancer cells." (PMID 32283687, 2020). "One study investigated IL-6 level changes in six months following primary treatment in ovarian cancer patients." (PMID 32235786, 2020). "Collectively, our data revealed IL-6R as a receptor of IL-6 mediated the regulation of PD-L1 by interrupting the miR-21/IL-6 crosstalk, thus promoting ovarian cancer immune escape." (PMID 32927431, 2020). "They further reported that treatment with siltuximab, an anti-IL-6 antibody, significantly enhanced the therapeutic efficacy of paclitaxel in mouse models of epithelial ovarian cancer." (PMID 32375852, 2020). "Our study also stated that M2 macrophages increased the expression of PD-L1 and miR-21 in ovarian cancer cells via induction of IL-6." (PMID 32927431, 2020). "In ovarian cancer, IL-6 and VEGF are critical cytokines that are largely secreted in tumor tissue and ascites and are associated with many worse prognosis factors in ovarian cancer, which take part in angiogenesis." (PMID 32190078, 2020). "In the next step, we examined the clinical and prognostic relevance of IL-6 and the percentage of PD-L1/PD-L2 positive monocytes/macrophages (MO/MA) in terms of their clinical and prognostic relevance in ovarian cancer patients." (PMID 33062717, 2020). "Here, we demonstrate that cisplatin and nanocurcumin treatment suppressed the JAK/STAT3 pathway and reduced IL-6 expression, suggesting that the JAK/STAT3 pathway mediates the autocrine production of IL-6 in the ovarian cancer model." (PMID 33536913, 2020). "Other cytokines secreted by TAMs that induce the invasive potential of ovarian cancer cells are IL-6 and TGF-β." (PMID 32456078, 2020). "The knockdown of IL-6 and IL-8 was shown to sensitize the tumor cells to cisplatin treatment in lung and ovarian cancer, respectively." (PMID 32727400, 2020).
ovarian carcinoma (continued). "On the contrary, resveratrol neutralizes the effect of IL-6 on ovarian cancer cells and reduces level of STAT3 expression." (PMID 31949487, 2020). "AZD1480, a JAK 1/2 inhibitor, was evaluated in the treatment of interleukin-6 (IL-6)-driven cancers, including prostate, breast, and ovarian cancer." (PMID 32545187, 2020). "IL-6 in the malignant ascites, serum and plasma of patients with advanced ovarian cancer have been shown to correlate positively with advanced disease and poor survival." (PMID 32042020, 2020). "In line with our results in a chronic inflammation model, IL6 has also been reported to increase epithelial tumoral cell proliferation, migration and invasion in an ovarian cancer model." (PMID 32209102, 2020). "The constitutive expression of IL6 by ovarian cancer cells stimulates TAMs of the tumor microenvironment thereby promoting tumor growth." (PMID 32727400, 2020). "IL-6 secreted from M2 macrophages stimulated the expression of PD-L1 and miR-21 in ovarian cancer cells." (PMID 32927431, 2020). "IL10, IL6, IL6ST, and macrophage scavenger receptor 1 (MSR1; CD204) were positively correlated with ovarian cancer patients in the high-risk group using heatmap analyses of the signature with the immune-related genes." (PMID 33381581, 2020). "A recent study reported that IL-6 was involved in Jumonji C-domain family 2- (JMJD2A/KDM4-) mediated progression of ovarian cancer." (PMID 33062717, 2020). "Improved OxPhos in ovarian cancer cells increase IL-6 production which facilitates tumor cell survival and proliferation, changing efficacy to chemotherapy, and reduce progression-free survival of ovarian cancer patients." (PMID 32211323, 2020). "Based on whole-genome cDNA microarray analysis, KRASG12D/K104Q decreased expression of NPIPA2, DUSP1 and IL6 in lung and ovarian cancer cells." (PMID 33060649, 2020). "By evaluating the levels of transcripts encoding IL‐6 and INHBA in tumour biopsies from ovarian cancer patients (n = 307) using the cBioPortal website, we found a significant association between the expression of these genes." (PMID 31436048, 2020). "A similar cytokine-based interaction was shown in ovarian cancer, implying IL-6, CXCL-5 and CXCL-10, which promotes self-stored glycogen utilization by cancer cells to fuel glycolysis and subsequent mitochondrial activity." (PMID 33080792, 2020). "While LIF is elevated in ascites fluid in ovarian cancer and can promote the generation of AAMs, it does so in an IL-6 and MCSF-dependent manner." (PMID 33069212, 2020). "Treatment with an anti-IL-6 neutralizing antibody reduced the number of platelets in tumor-bearing mice as well as in patients with ovarian cancer." (PMID 31337034, 2019). "This clinical trial was based on experimental studies showing that tocilizumab inhibits the tumor growth and angiogenesis induced by IL-6 that normally leads to ovarian cancer." (PMID 30927911, 2019). "Because ovarian cancer cell grow in the peritoneal cavity, secreted IL6 is likely to initiate its own cascades of oncogenic pathways, further highlighting the significance of ovarian cancer-TME interactions." (PMID 31426393, 2019). "In other studies, propranolol blocked the NE-induced invasiveness or interleukin-6 (IL-6) production in the ovarian cancer cell line SKOV-3." (PMID 31703453, 2019). "Metastatic and drug-resistant, recurrent ovarian cancer produces significantly higher IL-6 compared to matched primary tumors." (PMID 31409361, 2019). "In another study, researchers showed the first-line chemotherapeutic cisplatin to increase IL-6-producing myofibroblastic CAFs in ovarian cancer patients by activating the NFκB signaling pathway." (PMID 31409361, 2019). "A recent study also showed the implication of PYK2 in IL-6-dependant chemoresistance of ovarian cancer cells." (PMID 31043590, 2019).
ovarian carcinoma (continued). "Increased OXPHOS in ovarian cancer cells enhances IL-6 production, which promotes cancer cell survival and proliferation, impairs responsiveness to chemotherapy, and shortens progression-free survival of ovarian cancer patients." (PMID 30626133, 2019). "In ovarian cancer, IL-6 increases thrombopoietin expression by hepatocytes, which increases platelet production by megakaryocytes providing an additional link between inflammation and platelet-dependent thrombin generation." (PMID 30654498, 2019). "A previous study showed that IL-6 has the ability to induce apoptosis in many human ovarian cancer developments by blocking the IL-6R/STAT3 pathway." (PMID 31783838, 2019). "Ovarian cancer CAFs can indirectly induce angiogenesis through increased secretion of pro-inflammatory factors IL-6, COX-2, and CXCL1." (PMID 30380628, 2018). "Increased secretion of IL-6 was also noted after a bone marrow, amniotic membrane, and decidua MSCs co-culture with ovarian cancer cell lines (SKOV-3 and IGROV-1) and endometrial cancer cell line (Ishikawa)." (PMID 30310111, 2018). "Perhaps the most abundant cytokine accumulating in the plasma and ascitic fluid of ovarian cancer patients is IL‐6,124 a pro‐inflammatory cytokine secreted in large amount by CAFs and ovarian cancer cells." (PMID 28926101, 2018). "Treatment with P-3Fax-Neu5Ac significantly inhibited IL-6 and IL-8 mRNA expression and the ability of ovarian cancer cells to grow in an anchorage-independent manner in a soft-agar assay." (PMID 28288142, 2017). "Elevated interleukin 6 (IL-6) in ascites and in the serum of patients with advanced ovarian cancer has been most strongly correlated with poor survival as it has in multiple other cancers." (PMID 29163543, 2017). "For instance, IL-6 is elevated in a variety of malignant tumors, including gastrointestinal cancer, renal cell carcinoma, prostate cancer, epithelial ovarian cancer, lung cancer, Kaposi's sarcoma, and glioblastoma." (PMID 29163847, 2017). "Our findings support future research into two potential interactive immunotherapeutic targets, TNFR2+ Tregs and IL-6, to help enhance effective antitumor responses in patients with ovarian cancer." (PMID 29163543, 2017). "Supplementation of culture medium with Neu5Ac stimulated expression of IL-6 and IL-8 and rescued the tumor growth and migratory phenotypes of ovarian cancer cells expressing SHMT1 shRNAs." (PMID 28288142, 2017). "To this end, we asked if ectopic expression of IL-6 or IL-8 restores tumor growth in ovarian cancer cells expressing SHMT1 shRNA." (PMID 28288142, 2017). "Addition of Neu5Ac resulted in increased levels of IL-6 and IL-8 mRNA and protein in ovarian cancer cells expressing SHMT1 shRNA." (PMID 28288142, 2017). "To determine if SHMT1 loss-mediated downregulation of IL-6 and IL-8 also occurs in other ovarian cancer cell lines, we measured IL-6 and IL-8 mRNA levels in other ovarian cancer cell lines COV504 and COV413B expressing SHMT1 shRNA and observed similar results." (PMID 28288142, 2017). "Our results support earlier studies which showed that serum IL-6 levels positively correlate with the clinical disease status of women with ovarian cancer." (PMID 29051715, 2017). "IL-6/IL-6R signaling pathway, in particular, has been proposed to be a pivotal cytokine promoting ovarian cancer progression." (PMID 28821817, 2017). "For example in ovarian cancer, ovarian MSCs release IL-6 to promote proliferation and colony formation with a mechanism similar to that we observed with CXCR2 ligands." (PMID 29081734, 2017). "Third, SHMT1 promotes ovarian cancer tumor growth and progression, in part, by facilitating expression of pro-oncogenic inflammatory cytokines IL-6 and IL-8, and, at least in part, by regulating cellular levels of Neu5Ac." (PMID 28288142, 2017). "In a recent study in ovarian cancer, IL-6 was shown to induce defective angiogenesis through altered pericyte coverage in aortic ring vessels." (PMID 28978142, 2017).